KDM1A (lysine demethylase 1A)
Diseases named in the same sentence as KDM1A in open-access papers (continued):
Sharing a sentence is not in itself a finding about the gene and the disease.
lung carcinoma (60 papers, 2011 to 2025). "Next, we wanted to elucidate the underlying roles of the KDM1A-c-Myc axis in ferroptosis of lung cancer cells." (PMID 36357457, 2022). "We also used siRNA-mediated silencing of Kdm1a in cultured human teratocarcinoma PA-1 cells, lung carcinoma H1299 cells, and lung carcinoma H520 cells." (PMID 38346162, 2024). "We also utilized the TNMplot database to demonstrated that KDM1A was overexpressed in lung cancer tissues from RNA-Seq data and Gene-chip data." (PMID 36357457, 2022). "In summary, our work revealed the functional roles of KDM1A-c-Myc axis in the regulation of ferroptosis in lung cancer cells." (PMID 36357457, 2022). "GEPIA2 database showed that KDM1A expression was positively correlated with Myc expression in lung cancer." (PMID 36357457, 2022). "Our study has elucidated the effect of KDM1A/c-Myc regulatory axis in the ferroptosis resistance of lung cancer cells." (PMID 36357457, 2022). "Our data suggested that KDM1A confers resistance to ferroptosis in lung cancer cells through upregulating c-Myc signaling." (PMID 36357457, 2022). "In this study, lysine-specific demethylase 1 (LSD1/KDM1A) was found to be significantly upregulated in lung cancer cells and tissues." (PMID 36357457, 2022). "Pan-cancer analysis from UALCAN database revealed the upregulated expression levels of KDM1A in majority of cancers, including lung cancer." (PMID 36357457, 2022). "Based on several public bioinformatic databases, we found that KDM1A was over-expressed in lung cancer tissues." (PMID 36357457, 2022). "In our study, we found that KDM1A knockdown significantly repressed the expression of c-Myc, leading to the increased ferroptosis sensitivity of lung cancer cells." (PMID 36357457, 2022). "We found that ferroptosis-associated molecule, HMOX125, was significantly up-regulated in KDM1A knockdown lung cancer cells H1299 and A549." (PMID 36357457, 2022). "Recent studies have shown that KDM1A is overexpressed in multiple malignant tumours, including lung cancer, cervical cancer, oesophageal cancer and ovarian cancer." (PMID 31211500, 2019). "Using different lung cancer cell lines, we showed that targeting KDM1A by ORY-1001 can facilitate cell proliferation, cell cycle and apoptosis." (PMID 30568590, 2018). "In an effort to explore the role of KDM1A in lung cancer, we analyzed the correlation between KDM1A expression levels and the outcomes of lung cancer patients." (PMID 30568590, 2018). "Together, these data suggest that ORY-1001 affects the Warburg effect in lung cancer cells by targeting KDM1A, leading to the regulation of HK2 expression." (PMID 30568590, 2018). "Here, we report that KDM1A is highly expressed in lung cancers, where it appears to drive aggressive growth." (PMID 30568590, 2018). "In this study, we reported that KDM1A is highly expressed in lung cancer tissues and lung cancer cells and regulated cell proliferation." (PMID 30568590, 2018). "Together these data demonstrated that KDM1A was highly expressed in lung cancer and correlated with overall survival, and that KDM1A plays an important role in cancer cell proliferation, suggesting that KDM1A is a promising anti-cancer target." (PMID 30568590, 2018). "In the current study, we demonstrated that KDM1A is commonly upregulated in lung cancer and is important for cell proliferation." (PMID 30568590, 2018). "We found a negative correlation of EZH2 and MLL1 expression (PCC = −0.56) in colon cancer and positive correlation of EZH2 and KDM1A expression (PCC = 0.65) in lung cancer, suggesting cooperation between H3K27 methylation and H3K4 demethylation." (PMID 21886846, 2011). "In the present study, we aimedto identify circRNAs that derive from the LSD1-encoding KDM1A gene, and to investigate their potential to be released and uptaken by lung cancer versus non-cancer epithelial cells." (PMID 37762282, 2023).
lung carcinoma (continued). "Moreover, knockdown of KDM1A increased ferroptosis of lung cancer cells through downregulating c-Myc expression." (PMID 36357457, 2022). "Therefore, our findings collectively demonstrated the important roles of KDM1A-c-Myc signaling in the regulation of cell ferroptosis, and revealed a potential therapeutic strategy against lung cancer." (PMID 36357457, 2022). "Accordingly, our study displayed the upregulated KDM1A in lung cancer H1299 and A549 cells." (PMID 36357457, 2022). "Here, we evaluated the potential roles of KDM1A-c-Myc axis in lung cancer." (PMID 36357457, 2022). "In addition, GEPIA2 database showed that KDM1A expression was negatively correlated with HMOX1 expression in lung cancer." (PMID 36357457, 2022). "And we demonstrated that knockdown of KDM1A could significantly inhibit c-Myc expression levels in lung cancer cells H1299 and A549." (PMID 36357457, 2022). "We first examined the expression of KDM1A in lung cancer tissues using Oncomine data." (PMID 30568590, 2018). "From a translational point of view, therapeutic targeting of KDM1A might be an effective therapeutic option for the advanced growth of lung cancer, as it is sufficient to block the glycolysis signaling pathway." (PMID 30568590, 2018). "Furthermore, lung cancer patients with higher KDM1A levels have worse survival outcomes than patients with lower KDM1A levels." (PMID 30568590, 2018). "To determine the role of KDM1A in lung cancer cell proliferation, we found that knockdown of KDM1A by siRNA transient transfection, resulted in decreased cell proliferation in the human lung cancer H1299 and A549 cells." (PMID 30568590, 2018). "Then, we investigated whether KDM1A mediates ferroptosis of lung cancer cells." (PMID 36357457, 2022). "Therefore, targeting KDM1A could be a potential ferroptosis-based treatment strategy for lung cancer patients." (PMID 36357457, 2022). "Then, we investigated whether KDM1A mediates Myc signaling in lung cancer." (PMID 36357457, 2022). "In addition, we detected the expression profiles of KDM1A in several lung cancer cells." (PMID 36357457, 2022). "LSD1 (or KDM1A), the earliest reported and most studied KDM demethylase, exhibits abnormal overexpression and is a typical oncogene in lung cancer." (PMID 36420141, 2022). "Therefore, KDM1A might mechanistically mediate the demethylation of c-Myc in lung cancer cells." (PMID 36357457, 2022). "Knockdown of KDM1A inhibited the level of c-Myc and increased the concentration of malondialdehyde (MDA) and irons in human lung cancer cells H1299 and A549." (PMID 36357457, 2022). "In an effort to determine the role of HK2 in lung cancer mediated by KDM1A, we analyzed the correlation between HK2 expression levels and the outcomes of lung cancer patients." (PMID 30568590, 2018). "Next, we attempted to verify whether the effect of KDM1A inhibition by ORY-1001 on the Warburg effect, involved lung cancer cell proliferation and apoptosis." (PMID 30568590, 2018).
colorectal cancer (54 papers, 2011 to 2025). A primary or metastatic malignant neoplasm that affects the colon or rectum. "In colorectal cancer, miR-137-3p is low expressed and suppresses migration of colorectal cancer cells via regulating a KDM1A-dependent EMT process." (PMID 33968763, 2021). "MiR‐137‐3p, identified as a potential therapeutic target, suppresses the progression and metastasis of colorectal cancer cells by mediating the KDM1A‐dependent epithelial‐mesenchymal transition." (PMID 34288551, 2021). "KDM1A plays a role in activating the Wnt/β-catenin signaling pathway, but, at the same time, downregulates the signaling pathway antagonistic to the colorectal cancer-related gene dickkopf-1 (DKK1)." (PMID 29921310, 2018). "The inhibition of KDM1A attenuates Wnt/β-catenin signaling and diminishes colorectal cancer progression by downregulating the expression of LGR5." (PMID 29921310, 2018). "Moreover, increased expression of KDM1A is also associated with the expression of leucine-rich repeat-containing G-protein-coupled receptor 5 (LGR5), a well-known colorectal cancer stem cell marker." (PMID 29921310, 2018). "KDM1A (LSD1) is a H3K4/H3K9 demethylase that is overexpressed in GBM, which is consistent with similar overexpression in bladder, lung, and colorectal cancer." (PMID 37205197, 2023). "Upregulated expression of LSD1 (KDM1A) has been found in various human cancers, including AML, ovarian, lung, bladder and colorectal cancers." (PMID 28148257, 2017).
small cell lung carcinoma (53 papers, 2013 to 2025). Small cell lung cancer (SCLC) is a highly aggressive malignant neoplasm, accounting for 10-15% of lung cancer cases, characterized byrapid growth, and early metastasis. "Upregulation of LSD1 (KDM1A), which catalyzes demethylation of H3K4Me2/Me1 and possibly H3K9Me2/Me1, was observed in small cell lung cancers relative to normal lung tissues." (PMID 24130964, 2013). "Based on these recent findings, 3 different KDM1A small molecule inhibitors, namely tranylcypomine, GSK-LSD1, and ORY-1001, are currently in phase I/II clinical studies for AML and small cell lung carcinoma." (PMID 30619733, 2018).
melanoma (50 papers, 2014 to 2026). A malignant, usually aggressive tumor composed of atypical, neoplastic melanocytes. "Genetic or pharmacological inhibition of histone demethylase LSD1 (also known as KDM1A) also stimulates ERV expression in melanoma." (PMID 36497341, 2022). "Notably, the introduction of LSD1/KDM1A inhibition (targeting a H3K4me1/2 and H3K9me1/2 demethylase) in a melanoma mouse model resulted in IFN signaling induction and sensitization to checkpoint inhibition, thus stimulating tumor immunogenicity." (PMID 39766049, 2024). "Besides, KDM1A ablation has been reported to stimulate anti-tumor immunity and enable the PD-1 blockade in melanoma." (PMID 39638799, 2024). "While Kdm1a protein levels did not significantly correlate with melanoma differentiation state, Znf217 was among the top 4% proteins that correlated with the expression of Axl relative to Ngfr." (PMID 33750776, 2021).
glioblastoma (36 papers, 2013 to 2025). The most malignant astrocytic tumor (WHO grade IV). "KDM1A-mediated transcriptional repression of these genes underlies the self-renewal of cancer stem cells and glioblastoma progression." (PMID 29921310, 2018). "For their part, LSD1/KDM1A inhibitors are still in pre-clinical studies for glioblastoma/glioma and medulloblastoma, while they are advancing into the early phase for other clinical indications (hematologic malignancy and solid tumors)." (PMID 40862786, 2025). "Remarkably, SUCLG2 was reported downregulated also in KDM1A-silenced glioblastoma cells confirming a positive correlation between KDM1A and SUCLG2." (PMID 37385999, 2023). "KDM1A also decreases H3K4me3 at the c-Myc locus and reduces the expression of Myc29 as well as its target genes in glioblastoma cells." (PMID 33462212, 2021). "In glioblastoma, KDM1A was stabilized via phosphorylation, which was triggered by glycogen synthase kinase 3β." (PMID 31737960, 2020). "GSK3β was shown to be upregulated in glioblastoma cells, and assist in stem cell maintenance by phosphorylating and stabilizing KDM1A." (PMID 29053791, 2017). "The phosphorylation of KDM1A has been observed during the progression of human glioblastoma." (PMID 29921310, 2018).
colon carcinoma (34 papers, 2011 to 2025). "An example of HDM can be amine oxidase lysine-specific demethylase 1 (LSD1/KDM1A), which was described to affect the clinical outcome and recurrence risk in various cancers, including colon cancer." (PMID 36296970, 2022). "The expression of KDM1A is also associated with reduced expression of CDH1, which results in colon cancer metastasis." (PMID 29921310, 2018). "Moreover, the upregulated expression of KDM1A significantly reduced the expression of E-cadherin in samples of advanced colon cancer and distant metastases." (PMID 29921310, 2018). "In vitro pharmacological inhibition of KDM1A activity or siRNA knockdown of its expression significantly suppressed proliferation and invasion and induced apoptosis in colon cancer cells, suggesting that targeted inhibition of KDM1A may provide a new direction for the treatment of colon cancer." (PMID 40699666, 2025). "By endogenous co-immunoprecipitation, we found KDM1A to bind DNMT1 and DNMT3B in two different cancer cell lines: when we immunoprecipitated endogenous KDM1A from whole-cell extracts of the colon cancer cell line HCT116, we detected DNMT1 and DNMT3B by western blotting." (PMID 27449289, 2016).
Ewing sarcoma (34 papers, 2013 to 2026). A small round cell tumor that lacks morphologic, immunohistochemical, and electron microscopic evidence of neuroectodermal differentiation. "Lysine-specific demethylase 1 (LSD1), encoded by the gene KDM1A, is overexpressed and correlates with poor patient prognosis in Ewing sarcoma." (PMID 41732136, 2026). "Lysine Specific Demethylase 1 (LSD1/KDM1A) is often associated with the NuRD complex and in Ewing sarcoma is required to mediate the repressive function of EWS/FLI." (PMID 31231465, 2019). "We recently demonstrated that Ewing sarcoma cell lines are highly susceptible to KDM1A blockade with the small molecule inhibitor SP-2509." (PMID 30559927, 2018). "In a methylation analysis of 500 sarcomas, KDM1A was overexpressed in synovial sarcoma, rhabdomyosarcoma, osteosarcoma and Ewing sarcoma, and elevated expression is associated with a poorer prognosis in Ewing sarcoma." (PMID 40983796, 2025). "In the preclinical setting, inhibition of KDM1A/LSD1 using SP-2509, a reversible inhibitor, suppressed cell growth in a Ewing sarcoma cell line." (PMID 34349608, 2021). "Prolonged chronic exposure of the SP-2509 hypersensitive A673 Ewing sarcoma cell line (IC50 < 150 nM) to KDM1A blockade resulted in generation of a SP-2509 drug resistant cell line." (PMID 30559927, 2018). "We previously showed that SP-2509 treatment significantly decreases both KDM1A mRNA and protein levels in Ewing sarcoma cells." (PMID 30559927, 2018). "Based on the field's growing appreciation that EWS/FLI mediates epigenetic landscape regulation in Ewing sarcoma, we propose that KDM1A is critical for maintaining overall oncogenic competent chromatin configuration and conformation." (PMID 30559927, 2018). "As such, this study investigated Ewing sarcoma mechanisms of acquired resistance to the small molecule reversible lysine specific demethylase (LSD1/KDM1A) inhibitor SP-2509." (PMID 30559927, 2018). "However, a second group of researchers found that inhibition of KDM1A catalytic demethylase activity was insufficient as a therapeutic strategy for Ewing sarcoma in 3D spheroid tissue cultures." (PMID 34349608, 2021). "The upregulation of KDM1A is also observed in chondrosarcoma, Ewing’s sarcoma, and osteosarcoma." (PMID 29921310, 2018). "Moreover, a US Food and Drug Administration-approved drug that inhibits KDM1A was also found to inhibit chondrosarcoma, Ewing’s sarcoma, osteosarcoma, and rhabdomyosarcoma cell growth in vitro." (PMID 29921310, 2018). "Pishas and Lessnick concluded that SP-2509 resistance in Ewing sarcoma was not fully reversible or driven by direct mutation in KDM1A and, therefore, may have been due to other epigenetic mechanisms." (PMID 34349608, 2021). "Among them is iadademstat (ORY-1001) targeting KDM1A/LSD1 and used in AML, Ewing sarcoma, and triple negative breast cancer, but their effectiveness can be improved if combinatorial strategies with other drugs are identified." (PMID 37179361, 2023). "Several studies have reported overexpression of lysine specific demethylase 1A (LSD1), also known as KDM1A/BHC110 which regulates chromatin states through the removal of mono and dimethyl groups (H3K4 or H3K9) in both Ewing sarcoma cell lines and tumors." (PMID 30559927, 2018). "Inhibition of KDM1A either through genetic depletion (shRNA) or small molecule blockade (SP-2509), reverses the EWS/ETS-driven transcriptional signature in Ewing sarcoma." (PMID 30559927, 2018). "Indeed, the role of KDM1A and EWS/FLI in Ewing sarcoma development may involve processes of stochastic epigenetic exploration followed by selection through phenotypic fitness." (PMID 30559927, 2018).
non-small cell lung carcinoma (34 papers, 2012 to 2025). A group of at least three distinct histological types of lung cancer, including non-small cell squamous cell carcinoma, adenocarcinoma, and large cell carcinoma. "Another study showed that lysine (K)-specific demethylase 1A (KDM1A) promoted tumor cell invasion by silencing TIMP3 expression in non-small cell lung cancer cells." (PMID 29731768, 2018). "GSK-LSD1, a selective chemical probe for the histone lysine demethylase KDM1A (LSD1), and the irreversible EGFR-mutant selective kinase inhibitor osimertinib (now approved in non-small-cell lung cancer), exemplify this approach." (PMID 28697345, 2017).
ovarian carcinoma (31 papers, 2013 to 2025). A malignant neoplasm originating from the surface ovarian epithelium. "By recruiting KDM1A to the ERβ promoter, its expression is suppressed, which may increase the risk of ovarian cancer metastasis." (PMID 40290121, 2025). "While inhibition of KDM1A activity with tranylcypromine decreases migration of the SKOV3 ovarian cancer cell line, and restores global expression of H3K4me2." (PMID 33669182, 2021). "In support of a role for KDM1A in cell migration, its overexpression in several ovarian cancer cell lines increases cell motility." (PMID 33669182, 2021). "Meanwhile, the gene KDM1A, whose products are active in ovarian cancer cells, also appeared in this pathway." (PMID 34857007, 2021). "S2101, one of the most effective KDM1A inhibitors, can suppress ovarian cancer cell viability and stimulate apoptosis and autophagy by regulating the expression level of signalling pathways." (PMID 32762026, 2020). "KDM1A up‐regulated in ovarian cancer tissues of TCGA and Bonome, and the difference in Bonome was the most obvious, with the P value of 2.14E‐8." (PMID 32762026, 2020). "Taking KDM1A as an example, the protein expression level of KDM1A in ovarian cancer tissues was significantly higher than that in normal tissues." (PMID 32762026, 2020). "For example, the combination of trichostatin A and decitabine inhibits KDM1A expression and weakens the migration and invasion of ovarian cancer cells." (PMID 32762026, 2020). "Similar to ovarian cancer, the expression of RAD51 was remarkably downregulated in KDM1A deficient TE1 and K410 cells (p < 0.0001), whereas it was highly upregulated in KDM1A overexpressing OE19 cells (p = 0.0058)." (PMID 39638799, 2024). "In ovarian cancer, the high KDM1A group was related to poor OS (p = 0.043) and PFS (p = 0.02)." (PMID 34925656, 2021). "Studies on ovarian cancer have indicated that KDM1A is overexpression in tumour tissue." (PMID 32762026, 2020). "Furthermore, KDM1A plays an important role in proliferation, invasion and metastasis in ovarian cancer." (PMID 32762026, 2020). "Furthermore, KDM1A acts as a coregulator for hormone receptors (AR, ER, GR, MR) and may control ERβ expression in ovarian cancer (OCa)." (PMID 39239542, 2024). "Therefore, according to our research and previous evidence, KDM1A may be a novel candidate signature for the mechanism of platinum response in ovarian cancer." (PMID 32762026, 2020). "Lysine-specific histone demethylase 1 (LSD1/KDM1A), the first histone demethylase identified, plays a pivotal role in the epigenetic regulation of gene expression and is frequently dysregulated in gynecological cancers such as cervical and ovarian cancers." (PMID 41029427, 2025). "The effect is not specific to ovarian cancer cells because the LSD1 enzyme (also known as lysine (K)-specific demethylase 1A, or KDM1A) is present and frequently overexpressed in many cancer cell types." (PMID 36840175, 2023).